PMS2 (PMS1 homolog 2, mismatch repair system component)
Diseases named in the same sentence as PMS2 in open-access papers (continued):
Sharing a sentence is not in itself a finding about the gene and the disease.
cancer (continued). "The variants in PMS2 and CHEK2 were classified as pathogenic in ClinVar, with reported cancer associations." (PMID 38136396, 2023). "Heterozygous functionally inactivating PMS2 variants, when converted to homozygosity by a somatic event, cause a MMR defect, and the resulting spontaneous mutator phenotype predisposes to cancer." (PMID 35451539, 2022). "We also identified medically actionable variants in eight other cancer-related SFs genes, including APC, MAX, MSH6, MLH1, PALB2, PMS2, SDHB, and TSC2." (PMID 36143288, 2022). "MLH1-/PMS2-/MSH6- cancer cases almost arose throughout the entire digestive tract: from the gastric antrum to the left colic flexur." (PMID 36387226, 2022). "From our findings it appears that stage II SBAs are enriched with MMR-d cancers and especially with those characterized by MLH1/PMS2 loss." (PMID 32761330, 2021). "The low penetrance of PMS2 in cancer is possibly due to the presence of homolog protein MLH3 which is able to bind MLH1 and partially function in MMR." (PMID 34489406, 2021). "The somatic, heterozygotous PMS2 frameshift deletion (AF of 50.7% in cancer genome) (NM_001322014: c.1239delA, p.D414Tfs*34) was supposed to cause a non-coding transcript variant." (PMID 34885191, 2021). "Given the high prevalence of PMS2 c.2002A>G founder GPV and the success of ASOs in targeting aberrant splicing, we sought to explore the possibility of using morpholinos for cancer prevention associated with this mutation." (PMID 34489406, 2021).
cancer (continued). "The expression of WDR4 was significantly correlated with mutations in 5 MMR genes (MLH1, MLH2, MLH6, PMS2, EPCAM) in several cancer types." (PMID 34282052, 2021). "This was confirmed by our analysis since all candidate CNVs that we have identified and that were found to affect the cancer genes PMS2, APC2, POU5F1, KANSL1, DOCK8 and TMTC3 are part of this category." (PMID 33503040, 2021). "MSI-H cancer cell lines such as DLD-1 (MSH6 deficiency) and DU-145 (MLH1 and PMS2 deficiencies) cells showed a greater susceptibility to KA39 than the MSS cancer cell line HT-29, pointing out a kind of synthetic lethality." (PMID 34203761, 2021). "For the three samples, the percentage of cancer cells was greater than 25%, all the microsatellites analysed were stable, and the loss of expression in MMR-IHC affected the MLH1 and PMS2 proteins, a situation typically observed in the case of sporadic dMMR." (PMID 34439357, 2021). "Comparison of histological grades revealed that patients with poorly differentiated carcinomas showed greater immunostaining for PMS2." (PMID 33247565, 2021). "Out of the signatures associated with MMR deficiency in cancer cells, only MMR-1 is related to the mutational pattern found in C. elegans mlh-1 and pms-2 mutants." (PMID 29636374, 2018). "Of seven MSI cases, five cases lost both MLH1 and PMS2 protein expression, and were assumed as sporadic cancer." (PMID 30680068, 2018).
cancer (continued). "Strikingly, PMS2, the ‘Cancer census gene’ most frequently involved in a copy number gain in the LP-WGS-set, was not ranked among the most frequently gained genes in the TCGA-set." (PMID 29371938, 2017). "The cancer spectrum in CMMRD appears to be related to the gene mutated; homozygous carriers of MSH6 and PMS2 mutations develop brain tumours in the first decade of life." (PMID 28381238, 2017). "They find several cancer biology relevant genes, such as AKT1, ARNT, and PMS2 and their literature analysis finds that 57% of the BEDMRs overlap with at least one gene that has more than three literature references related to cancer." (PMID 24653980, 2014). "We observed that cancers frequently had areas with restored expression of Pms2, Ercc1 and/or Xpf, even though surrounding areas of the cancers had reduced levels of Pms2, Ercc1 and/or Xpf." (PMID 22494821, 2012). "This study reports on our findings on mutation type, cancer risk and age of diagnosis in MSH6 and PMS2 families." (PMID 20487569, 2010). "In the current study we report on our findings on mutation type, cancer risk and age of diagnosis in 29 families (78 participants) with a mutation in MSH6 and 6 families (7 participants) with a mutation in PMS2." (PMID 20487569, 2010). "The mismatch repair gene PMS2 was also underexpressed in our MSI-H cancers (P = 0.003, Fold change 1.4)." (PMID 15298707, 2004). "Furthermore, in vitro studies using purified human MLH1 and PMS2 proteins found that MMR activity was significantly decreased with MLH1-E34A, and mutations in the ATPase domain of MLH1 are associated with cancer risk." (PMID 39615226, 2025).
cancer (continued). "Due to the reduced overall cancer risk, prophylactic surgeries, such as hysterectomy, are not routinely recommended for PMS2 carriers unless there is a strong family history of EC." (PMID 40452892, 2025). "This lower incidence may be due to the lower cancer penetrance observed in individuals and families with PMS2 PVs/LPVs." (PMID 40723192, 2025). "An attenuated form of CMMRD, typically presenting with LS-associated cancers and often associated with first cancer diagnoses in adulthood rather than childhood or adolescence, has been associated with a PMS2 founder variant in the Nunavik population." (PMID 39031223, 2024). "Due to the lower risk of cancer compared to the other genes, many PMS2 families likely did not fulfil the original or revised Amsterdam or Bethesda criteria for testing, and thus were not identified when these criteria were used to select patients for testing." (PMID 39334433, 2024). "PMS2:c.241G > T was identified by the initial cancer genomic profiling test with F1CDx." (PMID 36647049, 2023). "Altogether, in 38.5% of these cases, MLH1 and PMS2 expression were negative, which can either refer to sporadic cancer of different causes or disease-causing germline variants in the MLH1 or PMS2 gene." (PMID 37509324, 2023). "In these cancers, the loss of MLH1/PMS2 protein expression is detected by immunohistochemistry." (PMID 37599324, 2023). "IHC analysis demonstrated that MLH1-/PMS2- was the most prevalent pattern in all cancer types." (PMID 37953261, 2023).
cancer (continued). "An older median age at diagnosis was observed for cancers in path_MSH6 and path_PMS2 carriers." (PMID 37181409, 2023). "For individuals with PMS2 variants, hyst-BSO at age 50 years was optimal and all other strategies were dominated; hyst-BSO at age 50 years was associated with an estimated cancer incidence of 0.68% and cancer mortality of 0.29%." (PMID 34499134, 2021). "Protein loss of MLH1/PMS2 was found in two and MSH6 loss in one cancer with MSI." (PMID 32144630, 2020). "The retrospective nature of our study and the paucity of individuals with pathogenic variants in PMS2 and MSH6 necessitated wide confidence intervals that may have led to an underestimation of cancer types in these two groups." (PMID 30386444, 2018).